CAT (catalase)
Diseases named in the same sentence as CAT in open-access papers (continued):
Sharing a sentence is not in itself a finding about the gene and the disease.
adenocarcinoma (9 papers, 2009 to 2024). A common cancer characterized by the presence of malignant glandular cells. "Our results showed decreased CuZnSOD, CAT, and Nrf2 levels, and increased GPx and GR levels in hyperplasias, while in patients with adenocarcinoma, the level of CAT was decreased and GR was increased, compared to benign groups." (PMID 30978928, 2019). "In patients with hyperplasias and adenocarcinoma, the CAT mRNA level showed a tendency to decrease, while the GPx and GR mRNAs inclined toward increase, compared to PE and UM groups." (PMID 30978928, 2019). "Catalase activity was significantly decreased in adenocarcinoma patients (47%)." (PMID 20030853, 2009). "However, in the case of the SW1116 line derived from adenocarcinoma, an increase in CAT activity was observed after administration of 5FU and cisplatin, suggesting that these compounds may contribute to a greater extent to the inhibition of neoplastic cell proliferation." (PMID 39195258, 2024). "In addition, p,p′-DDE-induced adenocarcinoma cell viability and proliferation were decreased by NAC, SOD or CAT." (PMID 25386960, 2014).
inflammation (9 papers, 2016 to 2025). Aberrant reaction of the microcirculation characterized by movement of fluid and leukocytes from the blood into extravascular tissues. "CAT reduces the production of reactive oxygen species to remove hydrogen peroxide and inhibit pancreatic inflammation." (PMID 35745003, 2022). "Here, Escherichia coli Nissle 1917 (ECN), a kind of oral probiotic, was genetically engineered to overexpress catalase and superoxide dismutase (ECN-pE) for the treatment of intestinal inflammation." (PMID 35701435, 2022). "Similar to our findings, it has been repeatedly shown that LPS-induced neuro-inflammation leads to a rise in the level of MDA while leading to a fall in glutathione, thiols, SOD, and CAT." (PMID 31579451, 2019). "Our study provides the first insights into how BK channel activation can inhibit oxidative stress pathways during pulmonary inflammation by restoring SOD and catalase levels in BALF cells and reducing H2O2 production, although other protective mechanisms cannot be ruled out." (PMID 40830381, 2025).
heart diseases (6 papers, 2015 to 2024). "The oxidation status of major biological pathways involved in cardiac disease and aging was affected by catalase overexpression, including cellular stress response, proteostasis, antioxidant systems, apoptosis and myocardial contractile apparatus." (PMID 26642319, 2015). "We aimed to provide evidence that by overexpressing catalase, reactive cysteine thiols are maintained in a functional state and protected from the irreversible oxidation observed in cardiac disease and aging." (PMID 26642319, 2015). "In an attempt to ameliorate cardiac diseases and delay aging by decreasing oxidative stress, mouse models overexpressing cellular antioxidant enzymes, including catalase, were created." (PMID 26642319, 2015). "In conclusion, our data suggest that catalase may alleviate cardiac disease and aging by moderating global protein cysteine thiol oxidation." (PMID 26642319, 2015).
psychiatric disorder (6 papers, 2019 to 2026). A disorder characterized by behavioral and/or psychological abnormalities, often accompanied by physical symptoms. "While it is highly contested whether the antioxidant system is upregulated or downregulated in psychiatric disorders, many studies demonstrate changes in superoxide dismutases (SODs), catalase (CAT), and glutathione peroxidases (GPXs) that correlate with mental health issues." (PMID 36902145, 2023). "Studies evaluating levels of the lipid peroxidation products and antioxidant enzymes CAT, SOD, and GSH-Px in psychiatric diseases have reported very different findings." (PMID 39473913, 2024). "Superoxide dismutase, CAT, and GSH-Px have been measured as antioxidants and MDA as an oxidative stress marker in numerous studies of psychiatric diseases." (PMID 39473913, 2024).
retinopathy (5 papers, 2014 to 2024). "Catalase concentrations were higher in the group with retinopathy [DM(+)PDR(+)] compared to the other groups studied in all matrices analyzed; this increase was significant in the aqueous and vitreous humors compared to the other two groups (p < 0.001)." (PMID 39768296, 2024). "Based on the crucial role of oxidative stress on cataract and retinopathy, the effects of PWCG on oxidative stress markers including level of MDA and the activities of SOD, CAT, and GPx in lens were carried out." (PMID 25614778, 2014).
respiratory diseases (4 papers, 2015 to 2025). "Furthermore, clinical evaluation of catalase-loaded nanogels (CAT-NGs) for ROS-driven respiratory diseases should also proceed to confirm efficacy and safety." (PMID 41009046, 2025). "The mechanisms of the effects of heat AT on respiratory diseases may include restraining the release of proinflammatory cytokines, inducing oxidative stress, for example, the increase in catalase and superoxide dismutase, elevating the adrenocorticotropic hormone and cortisol." (PMID 38522902, 2024).
brain diseases (3 papers, 2019 to 2022). "MnO2 has been demonstrated to exhibit catalase (CAT)- and superoxide dismutase (SOD)-mimicking activities, making it a promising free radical scavenger in the treatment of various brain diseases as a means to prevent neurons from being damaged." (PMID 35745695, 2022). "In brain diseases, cessation of the malondialdehyde (MDA) levels, increasing of reduced glutathione (GSH), recovery of the suppressed superoxide dismutase (SOD), and catalase (CAT) activities following UA administration suggest a protective effect in response to oxidative stress." (PMID 32184863, 2019).
skin disorder (3 papers, 2016 to 2020). Any deviation from the normal structure or function of the skin or subcutaneous tissue that is manifested by a characteristic set of symptoms and signs. "These skin disorders areassociated with skin catalase deficiency, resulting in elevated topicalH2O2 concentrations." (PMID 33188446, 2020).
immune system disorder (2 papers, 2022 to 2024). A disorder resulting from an abnormality in the immune system. "Here we have discussed the findings collectively and revealed a clear pattern of evidence of CM improving physiological effects of inflammatory diseases, oxidative stress and immune system disorders by increased GSH, SOD, GPx, TAC and CAT levels and reduced TNF-α, IL-17 and TGF-β." (PMID 35493477, 2022).
endocrine disorders (1 paper, 2022). "The results showed that low temperature induces endocrine disorders, affects basal metabolism and glucose metabolism, inhibits antioxidant enzyme activity (GST) and immune gene expression (AKP, CAT, GGT, and AKR1B1), and slows individual growth." (PMID 36139854, 2022).
hematologic malignancies (1 paper, 2021). "Bmal1 is a key component in hematologic malignancies, and the inactivation of BMAL1 promotes the progression of hematologic malignancies by disrupting the cellular circadian rhythm and impairing the characteristic circadian clock expression pattern of genes, including C-MYC, catalase, and p300." (PMID 33752691, 2021).
neurodevelopmental disorder (1 paper, 2014). A behavioral and cognitive disorder with onset during the developmental period that involves impaired or aberrant development of intellectual, motor, or social functions. "Catalase impairment has been observed in neurodegenerative conditions as well as in complex neurodevelopmental disorders such as autism spectrum, whose neurobiology is proposed to be associated with oxidative stress." (PMID 24729976, 2014).
CAT also shares sentences with these, for which no sentence is quoted: Parkinson’s (14 papers); Glucose intolerance (8); cerebral infarction (7); acute myocardial infarction (6); hypertriglyceridemia (6); alcoholic fatty liver disease (5); chronic periodontitis (4); liver dysfunction (4); myelogenous leukemia (4); prostate (4); adenomyosis (3); age-related macular degeneration (3); Chronic colitis (3); cognitive disorder (3); diabetic foot ulcer (3); essential hypertension (3); Fibroadenoma (3); Fusarium infection (3); keratitis (3); keratoconus (3); Oral ulcer (3); papilloma (3); vascular dementia (3); viral diseases (3); acute leukemia (2); aneurysm (2); aspergillosis (2); bladder transitional cell carcinoma (2); cardiac arrhythmias (2); chronic fatigue syndrome (2).
A further 201 diseases each share a sentence with CAT in 2 papers or fewer.